CD4 (CD4 molecule)
Diseases named in the same sentence as CD4 in open-access papers (continued):
Sharing a sentence is not in itself a finding about the gene and the disease.
infection (continued). "One of the main causes of HIV induced mortality is a secondary infection which develops due to a progressive decline of CD4 T cells." (PMID 35464779, 2022). "The H7N9 infection was also associated with a generally stronger CD4+ T cell response than the H9N2 infection." (PMID 36034707, 2022). "Next we used linear regression models to evaluate if pre-infection cytokine expression was associated with lowest CD4:CD8 ratio < 180 days post infection." (PMID 35165387, 2022). "Subjects with vaccine breakthrough infection had significantly higher CD4 and CD8 T cell responses targeting the vaccine-encoded Spike during the first and third/fourth week after PCR diagnosis compared to non-vaccinated controls, respectively." (PMID 36582222, 2022). "Throughout the course of infection, Ki67-associated proliferation increased but was matched in both CD4+ and CD8+ cells in the periphery (Figures E5E and E5F) and BAL (Figures E5G and E5H) of both groups of macaques." (PMID 35412961, 2022). "Recently, CyTOF has been used to interrogate the cellular subsets of CD4 T cells preferentially susceptible to productive infection by HIV." (PMID 35784348, 2022). "This is in part due to damage to the epithelia and mucosa caused by pre-existing infections, and also the associated immune inflammation, which increases the number of activated CD4+ T cells and macrophages present (the preferred host cells for HIV)." (PMID 35693831, 2022). "Memory CD4+ T cells can indirectly potentiate NK cell functions against infection caused by Pneumocystis murina, and depletion of CD4+ T cells significantly reduced the accumulation of NK cells and NK-cell mediated immunity." (PMID 36177012, 2022). "Further analysis of T cell subsets found that M. tuberculosis H37Ra i.n infection (UN) had negligible effect on proportions of CD4+ T cells, but caused a significant decline of CD8+ T cells in splenocytes." (PMID 36081510, 2022). "The parasite is known to be transmitted through the fecal–oral route via contaminated food or water, and the risk of infection is reported to be higher in persons with a CD4+ count of less than 100 cells/mL." (PMID 36355894, 2022). "Studies in mice infected with LP-BM5, a retrovirus which causes acquired immunodeficiency in mice, demonstrated infection-induced M-MDSC suppress CD4+ T cell and B cell responses." (PMID 35757733, 2022). "In fact, by using a panel of genetically deficient mice, a key role for IFN-γ-producer CD4+ T cells in restraining B. melitensis primary infection was unravelled, in contrast to the modest contribution of CD8+ T cells and B cell-mediated responses." (PMID 35888979, 2022). "Compared to HIV-1, HIV-2 is less pathogenic and is associated with a long asymptomatic phase after infection, reduced viral load and slower decline of CD4+ T cells." (PMID 33936106, 2021). "In the acute phase, SARS-CoV-2-specific CD4+ T cells have been associated with milder disease suggesting a role for this arm of adaptive immunity in the resolution of the infection." (PMID 34858405, 2021). "In this context, recent studies have shown that INH eliminates antigen-responding CD4+ T cells, which enhances the risk for post-treatment reactivation and re-infection of disease." (PMID 34415976, 2021). "We have previously shown that C. neoformans Δsgl1 confers complete protection against the WT infection in immunocompetent or CD4+ T cell deficient hosts." (PMID 34568097, 2021). "Kaplan-Meier analysis showed that the lower level of CD3+, CD4+ T cells, and CD4+/CD8+T cell ratio is associated with a greater risk of infection." (PMID 34568395, 2021). "Two immunofluorescence analysis of CD4+ and CD8+ T-cell in vitro infection concur to show that CD4+ T-cells are more susceptible to infection than CD8+ T-cells in sheep and cattle." (PMID 34452376, 2021). "The co-expression of IFN-γ and IL-10 by CD4+ T cells has been associated with protective responses induced by vaccination in experimental infection with T. cruzi." (PMID 34868005, 2021).
infection (continued). "Regardless, with each passing year, thus, the loss of CD4 T cells due to the infection gets larger and increasingly consequential, leading ultimately to disease progression." (PMID 33542308, 2021). "Infection with CRF55_01B was associated with lower CD4 count than infection with CRF07_BC both at diagnosis and the initiation of cART in this study." (PMID 34399785, 2021). "We and others have recently shown that IL-27 downregulates CD4+ T cell activation and prevents fatal liver pathology during infection with African trypanosomes, protozoan parasites causing serious infections in humans and animals." (PMID 33593983, 2021). "Together, these data suggest that vaccine-elicited spike-specific CD4+ T cells respond in the same manner to spike epitopes from the ancestral or variant strains, and would probably mount similar responses in vivo to infection by all three virus types." (PMID 34636722, 2021). "Activated, proliferating CD4+ T cells are highly susceptible to infection and support efficient HIV-1 replication." (PMID 34804062, 2021). "Consistent with previous studies, we report that treatment during hyperacute infection results in more rapid viral suppression with minimal CD4 count loss and suppression of detrimental T cell activation." (PMID 34630420, 2021). "Massive CD4 T-cell apoptosis during the acute infection phase is accompanied by profound immune activation, caused by release of apoptotic microparticles into the bloodstream." (PMID 35058937, 2021). "In Southern African adults, HLA-B∗57:03 and B∗58:01 have been associated with low set-point viral load and a higher CD4+ T-cell count during early infection - two phenotypes that positively correlate with LTNP status in adults." (PMID 34512729, 2021). "Infection with NTS serovars is known to stimulate an enhanced Th1-type bias by CD4+ or CD8+ T cells associated with increased production of proinflammatory cytokines IFN-γ, IL-18, IL-12, IL-15, and TNF-α." (PMID 33956909, 2021). "Infection- or vaccination-induced SARS-CoV-2 S–specific CD4+ T cells are indifferent to the S mutations of variants of concern." (PMID 34035118, 2021). "We next investigated M.tb lysate-specific CD4 T cell responses kinetics associated with acquisition of infection." (PMID 33610126, 2021). "Viral replication and associated inflammation persists in these tissues over the course of infection that is accompanied by damage to intestinal epithelial barrier, translocation of microbial products, immune activation and progressive loss of CD4 T cells." (PMID 33815419, 2021). "T cell exhaustion is an important mechanism involved in T cell dysfunction in chronic HIV infection; TIM-3 and PD-1 are markers of exhaustion involved in CD4+ T cell loss in untreated chronic HIV infection and CD4 restoration in treated infection." (PMID 34198803, 2021). "Like VNI, VNBI and VNBII are both also associated with lower CD4 counts which agrees with the general trend of C. neoformans causing infection in immunocompromised patients." (PMID 33808500, 2021). "Some studies have reported that lower CD4 count can affect mental health, possibly due to distress associated with infection progression." (PMID 33582967, 2021). "In a large HIV-1 vaccine trial (RV144), functional CD4+ T cell responses have been associated with reduced risk of infection." (PMID 34198973, 2021). "Meaningfully, higher CD4 T cell count and longer duration of infection were associated with decrease in A1 caliber of PLWH." (PMID 34239489, 2021). "Given that CD4+ T cells from NP as well as CD4+ T cells from PR are susceptible to direct, cis infection, the evidence supports the concept that the small amount of HIV-1 DNA detected is the result of direct infection." (PMID 33688006, 2021).
infection (continued). "Individuals infected with subtype C had lower probability to be deficient in CD4+ T cells when compared to subtype B. The HIV-1 epidemics in the South was characterized by high female-to-male infection ratios and women-to-child transmission." (PMID 34845263, 2021). "Across the endemic region, talaromycosis is estimated to have a pooled prevalence of 3.6% (range 0.13–19.63%) in people living with HIV/AIDS, with the greatest risk of infection in people with a CD4 cell count < 200 cells/mm3 (OR 12.68, 95%CI: 9.58–16.77)." (PMID 34228343, 2021). "Human immunodeficiency virus (HIV) is a life life-threatening and serious infection caused by a virus that attacks CD4+ T-cells, which fight against infections and make a person susceptible to other diseases." (PMID 33806939, 2021). "In contrast, another study reported that IL-17A-/- mice infected with L. donovani showed an increase in IFN-γ production by CD4+ T cells and better resistance against infection, suggesting that IL-17 promotes susceptibility to L. donovani infection." (PMID 33816344, 2021). "We found that the relatively resistant mouse strain had significantly more CD4+ and γδ T cells in their spleens than the relatively susceptible strain before infection and after infection with either ascarid species." (PMID 33431071, 2021). "Exhaustion of CD4+ T cells during LCMV Cl 13 infection has also been associated with chronic IFN-I signaling." (PMID 34696381, 2021). "The infection caused a robust influx of CD4+ T cells into the infected colonic LP, which also was unaffected by the early-life dysbiosis." (PMID 33531385, 2021). "A time-course analysis of ongoing immunity showed an immediate T cell response upon infection, associated with an acute increase of CD4+activated T cells in groups first infected with WT (WT/WT and WT/ΔPTX)." (PMID 34564636, 2021). "Compared to baseline, there was a progressive loss in %CD4+ T cell frequencies across the acute phase of infection (P = 0.0078) and the latter chronic phase of infection (P = 0.0003)." (PMID 34721397, 2021). "Upon influenza infection, activated CD4+ T cells polarized to both Th1 and Th2 phenotypes, but Th1 cells are associated with survival after the infection." (PMID 33917837, 2021). "We also found that levels of Siglec-9+ CD56dim NK cells inversely correlate with viral load during viremic infection and CD4+ T cell-associated HIV DNA during suppressed infection." (PMID 34762717, 2021). "IRIS occurs early during the rapid rise in CD4+ T cell numbers via LIP in HIV-infected patients with a history of viral infection or infection-associated inflammation that is well-controlled at the start of HAART." (PMID 33923792, 2021). "It was also associated with reduced proliferation of CD4+ T cells, as determined by the expression of Ki-67, until day 30 after infection." (PMID 34554927, 2021). "In particular, we have previously shown that the magnitude of PD-1 expression both at the CD8+ and CD4+ T-cell compartments, evaluated early after infection, was associated with the levels of subsequent viral persistence on cART." (PMID 34988339, 2021). "Among all differentially expressed T cell features CFP-10/ESAT-6-specific CD4 T cell activation was the best performing diagnostic biomarker of recent infection." (PMID 33610126, 2021). "In particular, low CD4+ counts and advanced disease are associated with a reduced chance of infection." (PMID 34442651, 2021). "Factors associated with rapid HIV disease progression (CD4+ T cell count < 350/μL within 2 years of infection) according to Cox regression analysis (n = 291)." (PMID 34367176, 2021). "The assay has been used to detect iATP level released by activated CD4+ cells and their correlation with the risk of rejection or infection." (PMID 33535640, 2021). "The reduced migration of CD4+ T cells to the lung parenchyma of pMT-10 mice was associated with reduced frequencies of CD4+ T cells expressing the early activation marker CD69 at day 23 after infection." (PMID 34554927, 2021).
infection (continued). "Next, the surface expression of HIV-1 coreceptors was evaluated to assess the potential susceptibility of CD4+ iNKT cells to infection." (PMID 34753817, 2021). "The uncertainty associated with the estimated recent increase is large, and the increase is likely to be linked to the decreasing proportion of infections diagnosed at a CD4 count of more than 500 cells per μL." (PMID 34118196, 2021). "An increased accumulation of immune-dysfunction-associated CD4+Foxp3+ regulatory T cells (Tregs) is observed in aging oral mucosa during infection." (PMID 33968777, 2021). "Defects in cellular immunity and CD4+ lymphopenia are the major predisposing factors for talaromycosis, as demonstrated by the high burden of infection in individuals with advanced HIV and other T cell immunosuppression." (PMID 34228343, 2021). "Elevated IL-15 in acute HIV regulates the susceptibility of CD4+ T cells to infection, thus playing a crucial role in viral reservoir establishment." (PMID 34578331, 2021). "Our study revealed that infection with CRF55_01B had significantly slower loss of CD4 count than infection with CRF01_AE among those with the initial CD4 count between 200 and 350 cells/μl." (PMID 34399785, 2021). "When the immune system is suppressed, the organism is more susceptible to infection due to the decrease in the CD4 + : CD8 + ratio." (PMID 33644058, 2021). "Apoptosis of uninfected bystander cells is a key element of HIV pathogenesis and represents a driving force to the important CD4+ loss which cannot be explained only by the direct infection." (PMID 33792105, 2021). "Associations between markers of prognosis of HIV infection such as viral load, duration of infection and CD4-cell count have also been associated with cardiovascular diseases." (PMID 34155234, 2021). "The correlates analysis also indicated that avidity of IgG for envelope, antibody‐dependent cellular cytotoxicity (ADCC) and phagocytosis (ADCP), and Env‐specific CD4+ T cells were inversely correlated with risk of infection." (PMID 34806296, 2021). "As an alternative strategy to deplete CD4 T-cells in the lungs during UgCl223 infection, we mimicked the loss of CD4-expressing T-cells observed in HIV by crossing CD4-Cre and Cre-inducible diphtheria toxin receptor (iDTR) mice to generate CD4DTR mice." (PMID 35186781, 2021). "The frequency of GC TFH cells in Tox2-deficient CD4+ T cells was significantly lower in both mLNs and spleens at days 7, 14, and 28 after infection." (PMID 34623911, 2021). "Cox regression analysis further confirmed that low CD3+, CD4+ T cells, and CD4+/CD8+ T cell ratio were independent risk factors of infection in CKD patients." (PMID 34568395, 2021). "Both age and severity of infection are independently associated with the changes in activated CD4+ cell proportions, as well as proportions of naïve, effector and activated CD8+ cells." (PMID 34025675, 2021). "This is associated with neonatal Foxp3− CD4+ T cells possessing a significantly increased capacity to produce IL-2 both before and after infection." (PMID 34665220, 2021). "Its expression is positively correlated with the susceptibility of T cells, monocytes, and macrophages to infection, and this is more substantial in resting CD4 T cells (in which HIV replication is silenced) than in activated CD4 T cells." (PMID 33987483, 2021). "BoHV-1 downregulates MHC-I, causes abortive infection and loss of CD4+ T lymphocytes, and interferes with the migration of lymphocytes and macrophages to the site of infection by counteracting chemokine activity." (PMID 33451136, 2021). "In contrast, a population of TH1 memory CD4+ T cells was identified as a strong predictor of reduced risk of infection." (PMID 34128836, 2021). "In line with increased CCR5 expression and activation status in stimulated T-PBMCs, CD4+ T cells from these cultures were more susceptible to infection by CCR5-tropic HIV-1 as compared with T-Pure cells." (PMID 34899645, 2021).
infection (continued). "We observed that DNA methylation patterns at interferon-related genes in monocyte cells associate with plasma viremia, CD4 T cell count, and Fiebig stage of infection, highlighting the utility of patient specific epigenetic signatures as biomarkers." (PMID 34388205, 2021). "Higher viral loads, lower CD4 T cell counts, HLA A*03 allele and infection with subtype C HIV were all independently associated with the development of neutralizing antibodies." (PMID 32879950, 2021). "Collectively, our results not only demonstrate the anomalous presence of CD4+ T cells in old sham mice but also show a deficient age‐related CD4+ T cells response in the CNS of mice subjected to TMEV infection as a model of progressive MS." (PMID 34355492, 2021). "HIV(IN:M50I) and HIV(IN:V151I) single mutation replicated at rates comparable with HIV(WT) in primary CD4(+) T cells from day one after infection; however, a variant containing both mutations exhibited impaired replication." (PMID 34835137, 2021). "In contrast, depletion of CD4+ T cells resulted in a loss of virally infected hepatocytes observed 2 weeks post-infection." (PMID 33376758, 2021). "Not surprisingly, and consistent with our previous findings, increased CD4 T-cell activation (CD4 DR+) and age at visit, which reflect the duration of infection within children, were associated with progressive disease." (PMID 33361123, 2020). "Overall, our data suggests that preferential infection of memory CD4+ T cell subsets by CCR5-using viruses is associated with the relative expression of CCR5 on each subset." (PMID 32762760, 2020). "The primary reservoir for HIV is within memory CD4+ T cells residing within tissues, yet the features that make some of these cells more susceptible than others to infection by HIV is not well understood." (PMID 32353080, 2020). "Clearly HIV exposure increased the amounts of isolated colorectal mucosal CD4+ T cell subsets that are susceptible to infection by HIV." (PMID 32876566, 2020). "CD4+ T-cell counts below 200 cells/mm3 contributed to the increased risk of TM infection in PLWHA (OR 12.68, 95%CI: 9.58–16.77)." (PMID 32727383, 2020). "A polymorphism in TLR7 (rs179008) is associated with increased viral loads and altered CD4 T cell counts during infection and is possibly associated with lower risk of transmission." (PMID 33202596, 2020). "Pox-protein vaccination elicits modest but potent CD4 T cell immunity and polyfunctional CD4 T cell responses correlated with reduced infection risk in RV144." (PMID 32881968, 2020). "Many experimental studies showed that resistance to infection with leishmania paraites is associated with the production of proinflammatory cytokines and activation of CD4+ Th1 response." (PMID 32656269, 2020). "Gut-associated CD4+ T cells are lost in several weeks after infection, followed by peripheral blood CD4+ T cells more than a year of infection." (PMID 33102204, 2020). "Our data here also support the association between the maintenance of CD4+ TSCM cells at normal levels with better control of infection." (PMID 32023301, 2020). "Depleting CD4+ T cells in PD-1-deficient mice during infection with Mbt rescued the animal's ability to survive infection." (PMID 32265932, 2020). "The extremely rapid depletion of CD4+ T-cells from gut-associated lymphatic tissue very early in infection also reflects the targeting of CD4+ T-cells." (PMID 32992787, 2020). "Our study found that patients with CD4+ T-cell counts below 200cells/mm3 had a higher risk of TM infection." (PMID 32727383, 2020). "In conclusion, our data suggest that resistance to infection conferred by fiber critically depends on a humoral response by type-specific virus neutralization, which can also be linked to systemic B cell and CD4+ T cell priming by vaccination." (PMID 33267862, 2020).